ERG (ETS transcription factor ERG)
Diseases named in the same sentence as ERG in open-access papers (continued):
Sharing a sentence is not in itself a finding about the gene and the disease.
cancer (continued). "ERG and SPINK1 expressing cancers do not appear to be strictly mutually exclusive molecular subtypes, although SPINK1 expression does appear to be uncommon in ERG-expressing cancers." (PMID 26172920, 2015). "Positive SENP1 immunostaining was seen in 41.7 % (ERG IHC) and 40.9 % (ERG FISH) of ERG positive cancers but in only 28.6 % and 30 % of cancers without ERG staining and ERG rearrangement, respectively (p < 0.0001 each)." (PMID 26202067, 2015). "Detectable SENP1 immunostaining was found in 41 % of ERG positive and in 47 % of PTEN deleted cancers but in only 30 % of ERG negative and 30 % of PTEN non-deleted cancers (p < 0.0001 each)." (PMID 26202067, 2015). "Data on both ERG FISH and IHC were available from 6076 cancers, and an identical result (ERG IHC positive and break by FISH or ERG IHC negative and missing break by FISH) was found in 5,811 of 6,076 (95,6%) cancers." (PMID 26230842, 2015). "SENP1 had no prognostic relevance in cancers harboring PTEN deletions, neither in ERG positive (p = 0.7745), nor in ERG negative cancers (p = 0.7267)." (PMID 26202067, 2015). "Data on both ERG FISH and IHC were available from 5,468 cancers, and an identical result (ERG IHC positive and break by FISH or ERG IHC negative and missing break by FISH) was found in 5,231 of 5,468 (95.7%) cancers." (PMID 25825985, 2015). "A comparison of non-malignant samples with either ERG-positive (1154 hits, FDR = 5%) or ERG-negative cancers (35 hits, FDR<5%) was additionally performed." (PMID 21814574, 2011). "The distinctive features include absence of carcinoma (in situ or invasive) and presence of tortuous and anastomosing vascular channels lined by atypical endothelial cells, which are positive for CD34, CD31, and ERG." (PMID 38403668, 2024). "Survivin immunostaining was absent in 61% of cancers with TMPRSS2:ERG fusion detected by IHC and 63% of cancers detected by FISH, but only in 32% of cancers without ERG staining and 33% of cancers without ERG rearrangements detected by FISH (P < .0001 each)." (PMID 31893572, 2020). "This also hold true for subsets of ERG positive, ERG negative and PTEN deleted cancers." (PMID 31534629, 2019). "A further analysis in the ERG-negative subset revealed that, for subgroups with identical classical and quantitative Gleason grades, BAP1 expression only had a prognostic impact for Gleason 3+4 carcinomas (p=0,006)." (PMID 31903168, 2019). "8p deletions were markedly more frequent in cancers with (53.5%) than without PTEN deletions (36.4%; P < 0,0001) and were slightly more frequent in ERG-positive (40.9%) than in ERG-negative cancers (34.7%, P < 0.0001) due to the association with the ERG-associated PTEN deletion." (PMID 27880722, 2017). "While there was a large number of Bx Neg and No Bx patients with a detectable TMPRSS2:ERG fusion event in our current study, TMPRSS2:ERG expression level (analyzed via RQ) was highest in the Bx Pos group consistent with the confirmed presence of cancer." (PMID 27144529, 2016). "This could be seen in all cancers, in the subsets of TMPRSS2:ERG positive or negative, PTEN deleted or undeleted carcinomas (p < 0.0001 each)." (PMID 25894226, 2015). "Moreover, the data demonstrated a strikingly poor disease outcome in a subgroup of 101 patients with ERG positive, PTEN deleted cancers with absent SOX9 expression." (PMID 26030748, 2015). "Cancer cells were also positive for K18 and AMACR, and negative for ERG." (PMID 23985008, 2013). "In the remaining 5 ERG-negative tumors, and in all 16 ERG-positive tumors, expression of the TIC was detectable, but at lower levels, and with only three minor exceptions, expression of the TIC was lower in cancer than in the matched normal sample." (PMID 21261984, 2011).
cancer (continued). "The majority of such biomarker tests, including the PCA3 test (PCA3 and KLK3), MiPS (serum PSA plus urine TMPRSS2:ERG and PCA3) and ExosomeDX Prostate Intelliscore (ERG, PCA3, SPDEF), rely on detecting transcripts from a very small number of genes which may not be expressed in every cancer." (PMID 34833048, 2021). "While some of these cancers might have identical precursor lesions if they develop from one high grade PIN, it is apparent from our data, that most multifocal cancers represent independent “de novo” tumors since more than 60 % of multifocal cancers had both ERG positive and ERG negative foci." (PMID 27530104, 2016).
adenocarcinoma (28 papers, 2011 to 2025). A common cancer characterized by the presence of malignant glandular cells. "This suggests that the TMPRSS2:ERG fusion gene is an early event but associated with progression from HGPIN to adenocarcinoma." (PMID 33634124, 2021). "Upon ERG activation, BasalLum cells give rise to the highly proliferative IM cells, which subsequently differentiate into invasive luminal adenocarcinomas." (PMID 40858905, 2025). "The few residual areas of ERG+ adenocarcinoma that retained Stat3 expression likely represent cells that escaped Stat3 knockout." (PMID 40858905, 2025). "ERG transgenic mice fail to develop invasive adenocarcinomas while the combined ERG/PTEN (Pb-Cre4; Ptenflox/flox; Rosa26ERG/ER) mice develop large invasive tumors." (PMID 31143708, 2019). "A recent genomic assay using fluorescence in-situ hybridization found that the adenocarcinoma and sarcomatoid components harbor ERG fusions, indicating the epithelial origin of the sarcomatoid component." (PMID 29581876, 2018). "A recent study showed that, ERG expressing mouse prostates developed adenocarcinoma in older mice through activation of YAP1, a critical component of Hippo pathway." (PMID 28439080, 2017). "Importantly, the cooperation of ERG gain and PTEN loss was recapitulated in mouse models whereby ERG transgenic mice crossed with PTEN-deficient mice developed frank malignant lesions and progression to invasive adenocarcinomas." (PMID 31143708, 2019). "ERG expression alone was not tumorigenic, but it did significantly accelerate adenocarcinoma development when coupled with Pten loss." (PMID 31520575, 2019). "Pathology review and immunohistochemistry for phenotypic markers (AR, PSA, PSMA, ERG, chromogranin A, synaptophysin, and CD56) showed that 9 research-ready PDXs are adenocarcinoma, 7 are neuroendocrine, and 1 has mixed pathology." (PMID 34413304, 2021). "Transduction of Trop2+CD49fHi prostate epithelial cells with activated AKT, ERG, and androgen receptor (AR) induces HGPIN and low-grade adenocarcinoma lesions in grafts obtained from prostate recombination assays." (PMID 27711225, 2016). "In both experiments, we found the fusion in 2/3 adenocarcinoma samples (SRX027124, SRX027125) and 1/3 adjacent normal sample (SRX027128) with reads spanning the fusion coordinate and containing both unique ERG and TMPRSS2 bases." (PMID 21589938, 2011). "The prostatic needle biopsy revealed adenocarcinoma (Gleason score, 5 + 4 = 9), which was ERG-negative by immunohistochemistry." (PMID 32034265, 2020). "Expression of ERG alone in prostate epithelia does not induce adenocarcinoma, but ERG is oncogenic when expressed in combination with PI3K/AKT activation, indicating an important synergy between these pathways." (PMID 24642271, 2014). "The presence of heterozygous Pten allele deletion on a C57/BL6 background led to the more rapid development of mPIN and adenocarcinoma lesions as compared to an FVB background, which decreased the sensitivity of observing a synergistic effect between ERG and Pten+/-." (PMID 22860005, 2012). "Interestingly, NEPC tumors haveTMPRSS2-ERG fusions at about the same rate as adenocarcinomas; however, owing to the lack of AR signaling, the expression levels of ERG are low in these tumors." (PMID 30135717, 2018). "Notably, unlike typical adenocarcinomas, such SmCCs do not consistently express ERG immunohistochemically, likely because of the lower frequency of expression of the androgen receptor (AR) by these cells." (PMID 29581876, 2018). "Also, transgenic ERG expression combined with heterozygous Pten deletion led to adenocarcinoma development in one study but not another." (PMID 22860005, 2012). "ERG expression, indicating a TMPRSS2-ERG fusion, is found in about 50% of SCNECs, which does not help to distinguish them from adenocarcinomas, as both show similar positivity rates." (PMID 40853482, 2025).
infection (10 papers, 2008 to 2025). The state of being infected such as from the introduction of a foreign agent such as serum, vaccine, antigenic substance or organism. "Infection of M12 cells with an ERG-encoding retroviral vector led to a marked increase in IGF1R levels in comparison to control (uninfected) cells." (PMID 27285981, 2016). "Then, the expression pattern of ERG was measured throughout infection and its expression level was found to be similar to that of lncRNA-ERGAL." (PMID 33014896, 2020). "CD69, CD31 and ERG triple positive cells were detected in the lungs 7 days post infection (dpi)." (PMID 40617350, 2025). "With infection, a reduction is also seen for ERG, a pan EC transcription factor." (PMID 37318981, 2023). "To analyze the potential role of Snd1 in this ERG-mediated phenotype, we isolated ERG-overexpressing and control primary prostate epithelial cells from mice with conditional Snd1 and deleted Snd1 using Adenovirus-Cre infection ex vivo." (PMID 37973913, 2023). "This might also be the case for ER: indeed, for the ERG proteins to be targeted (and thus, phosphorylated) by the host, the bacterial protein should be exposed to the host environment during the infection, namely in the form of reticulated bodies." (PMID 30930869, 2019). "To address the cell of origin using ERG, we isolated luminal and basal cells from multiple lobes of the prostates of Rosa26-ERGLSL/LSL; Ptenflox/flox (EP) mice, activated the EP genotype by infection with Ad-Cre virus and performed orthotopic implantations." (PMID 40858905, 2025). "Likewise, Ad-ERG-V5 infection of ECFAKKD and ECFAKY397F mutants restored both ERG and DLL4 levels back to those found in control pups, and also restored the vascular outgrowth phenotypes in these mice." (PMID 35723257, 2022).
cardiovascular disease (4 papers, 2019 to 2023). "In endothelial cells, the transcription factor ERG plays an essential role in establishing SEs, and variants associated with cardiovascular diseases are enriched in ERG TFBS localized in endothelial SEs." (PMID 35514262, 2022). "Enrichment of cardiovascular disease-associated single nucleotide polymorphisms at ERG super-enhancers suggests that ERG-dependent transcription modulates disease risk." (PMID 30892142, 2019). "The striking difference between the homeostatic versus oncogenic roles of ERG has important implications for the possible therapeutic potential of this pathway in pathologies associated with cardiovascular disease (CVD)." (PMID 30892142, 2019). "Taken together, these findings suggest that LINC00607 is involved in securing endothelial BRG1 and ERG-dependent target gene expression, as well as appropriate responses to stress and cardiovascular diseases." (PMID 36700983, 2023).
benign tumor (3 papers, 2015 to 2025). "RAH is a rare benign tumor, and the positive staining of markers, including ERG, FLI-1, CD31 and CD34, can contribute to its differential diagnosis." (PMID 40416971, 2025).
CNS tumors (2 papers, 2015 to 2021). "In our study we have demonstrated that unlike CD31 and CD34, ERG is exclusively expressed in endothelial cells within CNS tumors, lending support to the notion that ERG is a more specific marker for such cells." (PMID 25881913, 2015). "Using immunohistochemistry, and a specific rabbit monoclonal antibody, we evaluated ERG expression in CNS tumors." (PMID 25881913, 2015). "Our results show that ERG is a novel, reliable, and specific marker for endothelial cells within CNS tumors that can be used to better study the process of neovascularization." (PMID 25881913, 2015). "Overall, our results suggest that ERG is a novel, reliable, and specific marker for endothelial cells in CNS tumors that can be used to better study the process of neovascularization." (PMID 25881913, 2015). "In our study we observed that ERG was only expressed in the nuclei of endothelial cells lining vascular lumens in normal brain tissue and within CNS tumors, for example, in the glomeruloid microvascular proliferation seen in GBMs." (PMID 25881913, 2015). "We demonstrated significantly more extensive ERG expression in HBs than in other CNS tumors, including GBMs (threshold for statistical significance p < 0.05)." (PMID 25881913, 2015). "Our results revealed significantly higher ERG expression in HBs than in other CNS tumors, including GBMs, which had the fifth greatest mean EVI." (PMID 25881913, 2015). "In conclusion, we have shown that ERG is a novel and more reliable marker for endothelial cells within CNS tumors than CD31 and CD34 are, adding another tool to the arsenal for the evaluation of CNS tumors." (PMID 25881913, 2015). "However, a review of the literature indicates that very little has been done to assess the expression of ERG in CNS tumors, or to compare its reliability with that of other endothelial markers, such as CD31 and CD34." (PMID 25881913, 2015). "Furthermore, ERG dependably and intensely highlighted endothelial cells in CNS tumors, providing solid evidence that ERG is a more robust endothelial marker than CD31 and CD34 are." (PMID 25881913, 2015). "We observed significantly higher quantitative expression of ERG in HBs than in other CNS tumors." (PMID 25881913, 2015). "Furthermore, we have demonstrated that ERG expression is significantly higher in HBs than in other types of CNS tumors, including GBMs." (PMID 25881913, 2015). "Our studies demonstrated that in contrast to ERG, CD31 only variably highlighted endothelial cells within CNS tumors and sometimes demonstrated a notably weaker endothelial immunoreactivity." (PMID 25881913, 2015).
bacterial infections (1 paper, 2023). "Recent work interrogating human prostate tissues with active bacterial infections identified ERG+ precancerous lesions, suggesting that bacterial infections can initiate gene fusions associated with prostate cancer." (PMID 37179121, 2023).
heart disease (1 paper, 2022). "The results of our EGRET analysis support a previously unreported mechanism of action for ERG that may be disrupted in heart disease—that ERG regulates the expression of CSRP1 and that this regulation can be disrupted by genetic variation." (PMID 35193937, 2022).
hematopoietic cancers (1 paper, 2013). "We thus investigated ERG and TDRD1 co-expression by qRT-PCR in a panel of cell lines representing various hematopoietic cancers." (PMID 23555854, 2013).
kidney disease (1 paper, 2023). "We categorized patients based on molecular markers and found that the ERG+/SPINK1+ subgroup had higher postoperative kidney disease stages and serum creatinine levels compared to the ERG+/SPINK1− subgroup, suggesting a connection between SPINK1 overexpression and kidney function." (PMID 37894380, 2023).
vasculopathy (1 paper, 2021). "Based on the previous report that implicated lysosomal enzyme cathepsin B as a potential contributor to the development of SSc vasculopathy, we focused on its role in FLI1 and ERG protein degradation." (PMID 32979864, 2021).
ERG also shares sentences with these, for which no sentence is quoted: metastatic prostate carcinoma (9 papers); chronic myelogenous leukemia (8); myxoid liposarcoma (5); non-small cell lung carcinoma (4); soft tissue tumors (4); alveolar rhabdomyosarcoma (3); diabetes (3); neuroblastoma (3); pancreatic cancer (3); acute promyelocytic leukemia (2); age (2); Burkitt lymphoma (2); cavernomas (2); epithelioid sarcoma (2); fibrosis (2); gastrointestinal stromal tumor (2); hemangioblastoma (2); hematological malignancies (2); Hypertension (2); liposarcoma (2); lung small cell carcinomas (2); megakaryoblastic leukemia (2); pheochromocytoma (2); pilocytic astrocytoma (2); pulmonary arterial hypertension (2); renal carcinoma (2); abdominal aortic aneurysm (1); abscess (1); acute basophilic leukemia (1); acute erythroid leukemia (1).
A further 70 diseases each share a sentence with ERG in 1 paper.